RNU7-96P (RNA, U7 small nuclear 96 pseudogene)
Gene: Small nuclear RNA gene on chromosome 2 (97,913,054 to 97,913,117, reverse strand). Ensembl gene ENSG00000238719.
Homologues: Orthologues: chimpanzee U7 (100% identical), macaque U7 (80% identical), tropical clawed frog U7 (61% identical), tropical clawed frog U7 (59% identical), tropical clawed frog U7 (58% identical), tropical clawed frog U7 (56% identical), tropical clawed frog U7 (55% identical), tropical clawed frog U7 (53% identical), tropical clawed frog U7 (52% identical), tropical clawed frog U7 (50% identical). Paralogues in human: RNU7-62P (75% identical), RNU7-70P (75% identical), RNU7-143P (72% identical), RNU7-14P (72% identical), RNU7-30P (72% identical), U7 (72% identical), RNU7-125P (70% identical), RNU7-141P (70% identical), RNU7-18P (70% identical), RNU7-34P (70% identical), RNU7-56P (70% identical), RNU7-65P (70% identical), and 141 more.